NDRG3 (NDRG family member 3)
Diseases named in the same sentence as NDRG3 in open-access papers (continued):
Sharing a sentence is not in itself a finding about the gene and the disease.
tumor (25 papers, 2012 to 2026). "In immune cells, particularly tumor-associated macrophages, this NDRG3–Raf–ERK axis complements cytokine signaling and contributes to metabolic polarization by enhancing Arg1 and Vegfa expression in lactate-rich, hypoxic tumor regions." (PMID 40710349, 2025). "NDRG3 is a pro-tumorigenic member of the NDRG family in contrast to the other three members that are mainly associated with tumor suppressive functions." (PMID 35563842, 2022). "A Cox regression univariate analysis revealed that some factors were associated with DFS of HCC patients, including NDRG3 expression, tumor size, vascular invasion, and TNM staging." (PMID 30413609, 2018). "The results were in accordance with the findings of previous studies, which found that NDRG3 overexpression in tumors promoted tumor development and was associated with a poor prognosis." (PMID 30413609, 2018). "Notably, among four members of the family, NDRG1, 2, and 4 largely mediate tumor suppressive functions, while NDRG3 is associated with pro-tumorigenic functions." (PMID 35563842, 2022). "In addition, our analyses showed that NDRG3 expression was statistically associated with tumor size (P=0.048) and pathological grade (P=0.001)." (PMID 30413609, 2018). "NDRG3 is frequently overexpressed in many cancers, associated with aggressive cancer phenotypes and a poor prognosis, and shown to exhibit a number of pro-tumorigenic characteristics including promotion of tumor growth, angiogenesis, and metastasis (See Introduction)." (PMID 35563842, 2022). "NDRG3 promoted tumor growth and angiogenesis in HCC via signaling through Raf-ERK axis, and enhanced HCC metastasis via Wnt/β-catenin signaling by promoting nuclear translocation of β-catenin." (PMID 35563842, 2022). "In spite of the potentially unique position of NDRG3 in tumor biology among the NDRG members, its possible roles in the metabolism of cancer or normal cells were barely explored." (PMID 35563842, 2022). "NDRG family member 3 (NDRG3) has been proposed as a molecular marker of tumor, and is expected to be used in clinic." (PMID 36619553, 2022). "More interestingly, NDRG3 has been shown to be closely related to the regulation of tumour cells in a hypoxic environment." (PMID 35236459, 2021). "Consistently, HCC patients with low level of miR-192-5p in their tumor tissues and high level of NDRG3 or MCT1 in their non-tumor tissues had the shortest overall survival." (PMID 33256802, 2020). "While NDRG3 shares a high similarity to NDRG2 in terms of amino acid sequence and structure, NDRG3 exhibited remarkable structural differences in a flexible loop corresponding to helix α6 of NDRG2 that is responsible for tumor suppression." (PMID 31935861, 2020). "We have also found that lactate-induced pERK in environmental non-tumor cells partially relied on NDRG3 and MCT1." (PMID 33256802, 2020). "Since helix α6 in NDRG2 plays a pivotal role in tumor suppressor activity, the unfolded helix α6 region in NDRG3 seems to exert a different function from helix α6 of NDRG2." (PMID 31935861, 2020). "It has been suggested that the NDRG3 has a tumor suppressor role in BC patients, in which the triple negative and advanced stage BC tumors had the lowest levels of NDRG3 expression." (PMID 31286981, 2019). "Our qRT-PCR results indicated that HCC specimens had higher mRNA levels of NDRG3 than did normal non-tumor tissues." (PMID 30413609, 2018). "Of the 102 HCC specimens, 50 manifested NDRG3 overexpression (49.0%); however, of the 102 non-tumor specimens, only 27 (26.5%) had positive NDRG3 expression." (PMID 30413609, 2018). "A multivariate analysis was performed, which revealed that NDRG3 (P=0.002) indicated a poor DFS, whereas NDRG3 expression (P=0.005) and tumor size (P=0.033) were two independent predictors of prognosis for OS." (PMID 30413609, 2018). "Lactate-induced responses through the NDRG3–Raf–ERK axis are reported to be conducive for maintaining tumor progression under long-term hypoxia." (PMID 30413609, 2018).
tumor (continued). "AM is known to be involved in the early stage of the cellular mechanism of oxygen sensing, whereas NDRG3 is involved in the late phase; moreover, AM is involved in the regulation of the tumor microenvironment." (PMID 29179449, 2017). "Functionally, NDRG3 promotes tumor responses to hypoxia, such as anti-apoptotic, angiogenic, and proliferative processes, by activating the RAF (v-raf-1 murine leukemia viral oncogene homolog)-ERK (extracellular-signal-regulated kinase) pathway." (PMID 27447861, 2016). "Furthermore, NDRG3 overexpression enhanced T cell infiltration into tumors, improving their tumor-controlling capacity." (PMID 42136568, 2026). "In addition, lactic acid, the product of glycolysis, can also directly interact with N-myc downstream-regulated gene 3 (NDRG3) to protect tumor cells from PHD2 hydroxylation." (PMID 38139250, 2023). "Expression of the NDRG3 protein promotes angiogenesis in the tumor and the growth of its cells." (PMID 35330327, 2022). "Moreover, over-produced lactic acid from hyperglycolytic HCC cells stimulated the ERK phosphorylation of co-cultured LX2 and THP1 non-tumor cells partially via NDRG3 and MCT1, which in turn promoted cell malignancy and stemness of HCC cells." (PMID 33256802, 2020). "functional differences of NDRG3 in different tumor types, as in the case of NDRGs." (PMID 30413609, 2018). "MiR-122 negatively regulates the expression of a tumor promoter, N-myc downstream-regulated gene 3 (NDRG3), or pituitary tumor-transforming gene 1 (PTTG1) binding factor (PBF) whose upregulation, because of the loss of miR-122 expression, leads to the cell growth and invasion of the HCC tumor." (PMID 29673190, 2018). "Univariate and multivariate analyses revealed that NDRG3 expression was associated with DFS of HCC patients and can potentially be used as independent predictors of DFS, whereas NDRG3 expression and tumor size were identified as independent prognostic factors that affect OS." (PMID 30413609, 2018). "In addition, the xenograft animal study further shows that knockdown of NDRG3 enhanced the tumor growth of OECM-1 cells in vivo." (PMID 27589737, 2016). "In addition, we speculate that the increase of serum NDRG3 in the general population may play a role as tumor suppressor gene, while a role as carcinogenic gene under the combination of NDRG3 and accumulated lactic acid." (PMID 36619553, 2022). "In vitro overexpression of exogenous NDRG3 in PC-3 cells is reported to led to increased clone numbers, migration capabilities and growth rates compared with parental or mock empty vector transfected PC-3 cells, and in vivo overexpression of NDRG3 elevated xenograft tumor growth in nude mice." (PMID 30413609, 2018). "Some targets, such as DLX4, NDRG3, WNT1, MYC, CREB1, and SIRT6, are involved in tumor or cell proliferation." (PMID 39618816, 2024). "It has been found that NDRG3 is capable of activating RAF-ERK pathway under hypoxia and accelerating tumor occurrence and development through the accumulation of lactic acid." (PMID 36619553, 2022). "Treatment with IL30 also upregulated tumor progression genes, such as Ar (3.27 times), Bcl2 (3.25 times), IL6 (3.90 times), Cav2 (7.60 times), Ndrg3 (4.5 times), Sept7 (4.10 times) and Sfrp1 (7.46 times)." (PMID 36224639, 2022). "Up-regulated expression of NDRG3 then activates the Raf-ERK pathway and thereby promotes cell proliferation and angiogenesis, eventually resulting in tumour growth and progression." (PMID 35236459, 2021). "This is supported by the fact that upregulation of a NDRG3 paralogous, NDRG2, suppresses tumor invasion by inhibiting the matrix metalloproteinases MMP-9 and MMP-2." (PMID 33175867, 2020). "Compared with non-tumor tissues, HCC tissues showed significantly higher levels of NDRG3 protein (P<0.001)." (PMID 30413609, 2018).
tumor (continued). "In the present study, we used quantitative real-time reverse-transcription polymerase chain reaction (qRT-PCR) to analyze NDRG3 expression in HCC specimens and their neighboring non-tumor tissues." (PMID 30413609, 2018). "The results revealed that compared with non-tumor tissues, HCC tissues showed significantly higher NDRG3 expression." (PMID 30413609, 2018). "Unlike NDRG1 and NDRG2, NDRG3 facilitates tumor progression and metastasis via activating the WNT/β-catenin pathway." (PMID 40378957, 2025). "The accumulation of NDRG3 has been shown to activate rapidly accelerated fibrosarcoma in the Raf/extracellular signal-regulated protein kinase (Raf/ERK) pathway to mediate angiogenesis and the proliferation of tumor cells." (PMID 38139250, 2023). "As a member of the N-myc downstream regulatory gene families, NDRG3 has been reported to independently regulate the hypoxic response of tumour cells, but the relationship between NDRG3 and OA development has not been reported so far." (PMID 35236459, 2021). "There was no expression difference of NDRG3 or MCT1 in non-tumor tissues between HCC192Low and HCC192High patients." (PMID 33256802, 2020). "In both HCC cohorts, patients were divided into four groups based on miR-192-5p expression in their tumor tissues (HCC192Low and HCC192High, medium cut-off) and levels of NDRG3 and MCT1 in non-tumor tissues (NTHigh_NDRG3 or MCT1 and NT Low_NDRG3 and MCT1, medium cut-offs)." (PMID 33256802, 2020). "In vivo, HCC patients with low level of miR-192-5p in their tumor and high level of NDRG3/MCT1 in their non-tumor had the shorter overall survival when compared to other patient subgroups." (PMID 33256802, 2020). "Compared with the tumor suppressive NDRG members, NDRG3 has been reported to be oncogenic." (PMID 31935861, 2020). "Excessive NDRG3 expression in cells can up-regulate angiogenesis factors, such as CXCL1, CXCL3, and CXCL5, and their main role is to augment blood vessel growth to promote tumor growth." (PMID 30413609, 2018). "In addition, positive NDRG3 expression in HCC specimens is positively correlated with some clinicopathological parameters (e.g., tumor size and pathological grade)." (PMID 30413609, 2018). "Our results, which used β-actin as the internal control for normalization, revealed that HCC tissues had significantly higher NDRG3 expression (4.37 ± 0.527) than that of their neighboring non-tumor tissues (2.81 ± 0.292) (mean ± SEM values, P<0.05)." (PMID 30413609, 2018). "NDRG3 remains very stable once it is bound to lactate, even when cells are reoxygenated, which suggests that lactate–NDRG3–Raf–ERK axis-induced responses contribute to the maintenance of tumor progression under prolonged hypoxic conditions." (PMID 29562667, 2018). "Indeed, tumor growth in mice was successfully abolished by knocking-down HIF-1α and NDRG3 in combination." (PMID 27447861, 2016). "Unlike other NDRG members, which display tumor-suppressive properties, NDRG3 is believed to be oncogenic." (PMID 27447861, 2016). "While human NDRG3 shares similarity to NDRG2 regarding its amino acid sequence and structure, the crystal structure of NDRG3 demonstrated considerable structural differences in a flexible loop analogous to helix α6 of NDRG2 that is thought to be involved in tumor suppression." (PMID 40378957, 2025). "In addition, NDRG3 also up-regulate the expression of angiogenic chemokine 43 (CXCL1, CXCL3 and CXCL5), enhance the expression of Angiogen-44, thereby ultimately promoting tumor progression." (PMID 36619553, 2022). "For example, we did not detect NDRG3 expression in tumor cells from lymph nodes, which may be pivotal for the involvement of NDRG3 in HCC growth and metastasis." (PMID 30413609, 2018). "However, unlike NDRG1 and NDRG2, which are widely known as tumor suppressor genes, the role of NDRG3 in cancer is still inconclusive." (PMID 27589737, 2016).
cancer (13 papers, 2018 to 2026). A tumor composed of atypical neoplastic, often pleomorphic cells that invade other tissues. "However, further studies are needed to elucidate the underlying mechanisms involved in NDRG3 activity and its functional roles in various cancer types." (PMID 40378957, 2025). "In fact NDRG3 has been suggested to be regulated post-translationally in hypoxic cancer cells via lactate binding." (PMID 40378957, 2025). "Thyroid follicular epithelial cells and cancer cells showed positive expression of NDRG3, and the nucleus and cytoplasm were stained brown." (PMID 36619553, 2022). "In support of this model, a previous study showed that binding of lactate to NDRG3 in hypoxic cancer cells is sufficient to stabilize NDRG3 and activate Raf-ERK signaling." (PMID 36214665, 2022). "We chose to further pursue lactate, given that this metabolite, the end product of glycolysis, was previously shown to bind to NDRG3 in hypoxic cancer cells, resulting in NDRG3 stabilization and activation of Ras-Erk signaling." (PMID 36214665, 2022). "In hypoxic cancer cells, NDRG3 is stabilized by lactate and promotes angiogenesis and cell growth via activation of the Raf-ERK pathway." (PMID 36214665, 2022). "In glycolytic cancer cells, lactate activates an NDRG3/Raf/ERK tumor-growth pathway whereas it promotes mitochondrial biogenesis, pro-angiogenic signaling, and glutaminolysis in oxidative cancer cells." (PMID 33923958, 2021). "NDRG3 protein bound to lactate is upregulated by enhanced protein stability and accelerates cell growth and angiogenesis of cancer cells by activating the Raf-extracellular signal-regulated kinase pathway." (PMID 30497501, 2018). "Evidence has revealed that NDRG3 is a new and useful biomarker for human cancer; however, despite reports that NDRG3 is up-regulated in HCC specimens, its clinicopathological relevance and relationship to HCC prognosis remain unclear." (PMID 30413609, 2018). "In addition, some studies have found that NDRG3 may be a target for controlling the invasive behavior of hypoxic cancer cells." (PMID 36619553, 2022). "The decrease or increase of NDRG3 in cancer may be related to the state at that time." (PMID 36619553, 2022). "Northern and dot blot analysis demonstrated that NDRG2, NDRG3, and NDRG4 are highly expressed in adult human brain and almost undetectable in eight human cancer cell lines (HL-60, HeLa S3, K-562, MOLT-4, Raji, Daudi, SW480, and A549)." (PMID 40378957, 2025). "This review will focus on VHL-mediated signaling pathways involving the latest identified substrates/binding partners, including N-Myc downstream-regulated gene 3 (NDRG3), AKT, and G9a, etc., and their physiological roles in hypoxia signaling and cancer." (PMID 29562667, 2018). "NDRG3 may be involved in the pathogenesis of PTC as a tumor suppressor gene, the reason of which may be related to the metabolic transformation of cancer cells." (PMID 36619553, 2022). "Additionally, this work identifies NDRG3 as a previously undescribed regulator of RICD in T cells and reveals NDRG3 as a potential target for autoimmune disorders and chimeric antigen receptor T cell treatment for cancer." (PMID 42136568, 2026). "This study identified NDRG3 as the hypoxia-inducible lactate sensor that provides crucial hypoxia signaling of oxygen-dependent regulation in an HIF-independent manner; therefore, a combinatorial targeting of both HIF and NDRG3 might be a highly effective therapy in cancer." (PMID 29562667, 2018).
metabolic disorders (1 paper, 2021). "It has been previously reported that cardiomyocytes undergo hypertrophic changes due to elevated LDH activity, which stimulates NDRG3 expression by increasing lactate generation, followed by cell growth in animals with metabolic disorders." (PMID 33498641, 2021).
NDRG3 also shares sentences with these, for which no sentence is quoted: glioblastoma (1 paper); hepatitis C (1); ischemic stroke (1); liver cirrhosis (1); oral cancer (1); oral squamous cell carcinoma (1); osteoarthritis (1); thyroid nodule (1); von Hippel-Lindau disease (1).